MIR425 (microRNA 425)
Synonyms: hsa-mir-425; MIRN425; mir-425
Gene: MicroRNA gene on chromosome 3 (49,020,148 to 49,020,234, reverse strand). Ensembl gene ENSG00000199032.
Gene Ontology:
Biological process: miRNA-mediated post-transcriptional gene silencing
Cellular component: RISC complex
Homologues: Orthologues: chimpanzee ptr-mir-425 (100% identical), macaque mml-mir-425 (99% identical), guinea pig MIR425 (95% identical), mouse Mir425 (95% identical), dog MIR425 (93% identical), rat Mir425 (92% identical), pig ssc-mir-425 (89% identical), rabbit MIR425 (70% identical), tropical clawed frog xtr-mir-425 (69% identical).